RN7SL118P (RNA, 7SL, cytoplasmic 118, pseudogene)
Gene: Miscellaneous RNA gene on chromosome X (119,434,519 to 119,434,820, forward strand). Ensembl gene ENSG00000266420.
Homologues: Orthologues: chimpanzee Metazoa_SRP (100% identical), macaque Metazoa_SRP (97% identical). Paralogues in human: RN7SL1 (85% identical), RN7SL2 (85% identical), RN7SL3 (84% identical), RN7SL732P (83% identical), RN7SL45P (82% identical), RN7SL398P (81% identical), RN7SL126P (81% identical), RN7SL7P (81% identical), RN7SL230P (80% identical), RN7SL664P (80% identical), RN7SL296P (80% identical), RN7SL357P (80% identical), and 702 more.